HMGB1 (high mobility group box 1)
Diseases named in the same sentence as HMGB1 in open-access papers (continued):
Sharing a sentence is not in itself a finding about the gene and the disease.
tumor (continued). "Inflammation, including tumor-related inflammation, is the main factor contributing to the release of HMGB1; however, the release of HMGB1 from tumor cells themselves may also contribute to the high plasma concentration of HMGB1 in the tumor-bearing state." (PMID 35328684, 2022). "ROS produced in the process of PDT can cause apoptosis of tumor cells 9, accompanied by the release of damage-associated molecular patterns (DAMPs) including adenosine triphosphate (ATP) or calreticulin (CRT), and high mobility group box 1 (HMGB1) from dying tumor cells 10-13." (PMID 36276646, 2022). "Moreover, HMGB1 functioned as the executor of pyroptotic cell death to participate in the regulation of tumor immune microenvironment via the inhibition of mutant BRAF and MEK." (PMID 36267972, 2022). "Given the role of HMGB1 in the M1-like polarization of macrophages in vitro, we hypothesized that it may play a critical role in GB microenvironment to enhance anti-tumor immune responses." (PMID 35193644, 2022). "The capacity of HMGB1 to react to cellular stress signals and preserve lasting inflammatory process may prevent cancerogenesis and tumor growth." (PMID 36551568, 2022). "Tumor cells express calreticulin and secreted ATP as well HMGB1; NK and granulocyte recruitment." (PMID 35640930, 2022). "In HCC, HMGB1 was proved to interact with mitochondrial DNA to promote the activation of toll-like receptor (TLR)-9 signaling in hypoxia condition for the stimulation of tumor development." (PMID 36267972, 2022). "HMGB1 plays both oncogenic and tumor-suppressive roles in tumor development." (PMID 36589226, 2022). "In addition to its nuclear function, HMGB1 plays a role in inflammation, cell differentiation and migration and the tumor metastasis of the remaining cells after chemotherapy." (PMID 36429101, 2022). "Additionally, elevated UCA1 promotes tumor EMT progression and tumor invasion through the miR-143/HMGB1/UCA1 pathway (Table A1)." (PMID 36139386, 2022). "Therefore, the extracellular HMGB1 release from tumor cells exposed to photon beam irradiation or chemotherapy has been proposed as a therapeutic and prognostic biomarker." (PMID 35336794, 2022). "HMGB1 staining (green) was observed uniformly across the entire tumor from untreated mice." (PMID 33654071, 2021). "In general, ferroptosis is a form of inflammatory cell death associated with the release of DAMPs (e.g., high mobility group box 1 (HMGB1) and DNA) or lipid oxidation products (e.g., 4HNE, oxPLs, LTB4, LTC4, LTD4 and PGE2) during tissue injury or tumor therapy." (PMID 33268902, 2021). "It is unclear whether the tumour microenvironment affects the nuclear translocation of HMGB1 and whether nuclear translocation of HMGB1 is related to its post-translation modification." (PMID 33391448, 2021). "Interestingly, Nano-DOX also induced NF-κB-dependent RAGE expression in the tumor cells and thus reinforced HMGB1’s action thereon." (PMID 34488792, 2021). "Mounting evidence revealed that HMGB1 was an important tumor-promoting effector in HCC and targeting HMGB1 could significantly restrain HCC progression." (PMID 33747917, 2021). "Extracellular HMGB1 could be passively released from necrotic cells and actively excreted by inflammatory cells or tumor cells." (PMID 33661757, 2021). "HMGB1 was highly expressed both in the nucleus and in the cytosol of tumor cells." (PMID 33956406, 2021). "Exploration of the mechanism of EphB4 suggests that we may regulate the tumour microenvironment of OSCC through the HMGB1-mediated NF-κB signalling pathway." (PMID 34539874, 2021). "High mobility group box 1 (HMGB1) is reported to play a role in tumour development." (PMID 33391448, 2021). "Additionally, they analyzed the activation of tumor endothelial cells by showing significant decrease in their permeability with anti-HMGB1 antibodies." (PMID 34975408, 2021).
tumor (continued). "Finally, hypoxia-inducible factors (HIF-1α and 2α), high-mobility group box 1 protein (HMGB1), extracellular ATP, or tumor-derived ECM components are also potential factors that promote M2 polarization." (PMID 33418996, 2021). "For the positive aspects, the release of HMGB1 from dying tumor cells could force host DCs to process and present tumor antigens." (PMID 34459122, 2021). "Further studies will have to confirm these promising findings and show whether HMGB1 as a classical DAMP has additive value to established tumor markers." (PMID 33672622, 2021). "Platelet-tumor cell interactions mediated by platelet toll-like receptor 4 (TLR4) and tumor cell-released high-mobility group box 1 protein (HMGB1) lead also to the α-granule release and P-selectin exposure, subsequently increasing the number of extravasating tumor cells in lung vessels." (PMID 34322381, 2021). "The HMGB1 can be autocrine i.e. from the TAMs, or paracrine i.e. from the tumor cells." (PMID 34488792, 2021). "However, the release of DAMP’s in the TIME such as HMGB1 has also been shown to promote immunosuppressive pathways resulting in tumor immune escape contributing to tumor radioresistance." (PMID 33986291, 2021). "We demonstrated that the release of the damage associated molecular pattern (DAMP), high mobility group box 1 (HMGB1), from PV-10 injected tumors induced the activation of dendritic cells (DCs) which subsequently primed anti-tumor T cell responses in lymph nodes." (PMID 34187428, 2021). "In breast cancer patients, HMGB1 released from dying tumor cells facilitates the anti-tumor immune response by ligation of Toll-like receptors 2 and 4 on dendritic cells to enhance processing and presentation of tumor antigens." (PMID 34885056, 2021). "Furthermore, we detected low level of HMGB1 in mice serum EVs and tumor tissues treated with glycyrrhizin." (PMID 34867338, 2021). "Additionally, murine tumors treated with histotripsy have been found to have elevated levels of HMGB1, CRT, and HSP within the tumor and increased HMGB1 has been routinely found in serum following treatment." (PMID 34136405, 2021). "Notably, tumor-released exosomes transferred HMGB1 into B cells and then stimulated the expansion of the TIM-1+Breg cells through the mitogen-activated protein kinase (MAPK) and Toll-like receptor (TLR) 2/4 pathways." (PMID 34599143, 2021). "A study demonstrated that NETs can release HMGB1 and promote tumor metastasis." (PMID 34758877, 2021). "Killing tumor cells by chemotherapy through induction of ICD or immunogenic apoptosis results in the secretion of damage-associated molecular patterns (DAMPs), like calreticulin (CRT), high mobility group box 1 (HMGB1) and adenosine triphosphate (ATP)." (PMID 33865432, 2021). "Many studies are focused on the role of HMGB1 in inflammation and tumour progression." (PMID 33922955, 2021). "The main alarmin, HMGB1, released by pyroptotic cells, could promote tumor cell survival, which largely suggests that HMGB1 drives the accumulation of MDSCs by inducing autophagy, thereby maintaining MDSC viability." (PMID 34459122, 2021). "Emerging data have suggested that HMGB1 could promote tumour progression via promoting proliferation and invasiveness of cancer cells." (PMID 33191617, 2021). "In addition, HMGB1 was critical for the activation and intratumoral aggregation of tumor-infiltrating T cells to release lymphotoxin α1β2 and attract macrophages into the lesion, thereby accelerating tumor progression." (PMID 33925132, 2021). "Additionally, we observed decreased expression of the fibroblast biomarker α-SMA in tumour tissues with low expression of HMGB1." (PMID 34497155, 2021). "In addition, accumulating evidence has revealed that HMGB1 affects the malignant progression of tumours via NF-κB in different types of cancer." (PMID 34539874, 2021). "Immunostaining used in this study showed that abundant HMGB1 was expressed in most tumor tissues." (PMID 34257571, 2021).
tumor (continued). "Thus, blood-borne, platelet-derived exosomal HMGB1 putatively exerts pro-malignant effects through the tumor HMGB1/RAGE axis." (PMID 33669632, 2021). "We also explored the potential role of HMGB1 in neosis‐based tumor repopulation." (PMID 33523579, 2021). "However, necrotic tumor cells can release a large number of HSPs and HMGB1, which promote the maturation of DCs." (PMID 34588987, 2021). "Since the high expression level of TLR-4 is a kind of biomarkers of M1 macrophages 28, HMGB1 released from irradiated BCCs might assist in the anti-tumor activation of macrophages through TLR-4 pathway." (PMID 33867819, 2021). "However, it is important to mention that among these studies, HMGB1 expression levels have been analyzed in both tumor and blood samples." (PMID 33920544, 2021). "Moreover, HMGB1 was observed to incite apoptosis in macrophage-derived dendritic cells, subsequently dampening anti-tumor immunity." (PMID 33925132, 2021). "Additionally, compared to patients with low nuclear HMGB1 expression in the tumor, patients with high HMGB1 expression were more often diagnosed with a moderately differentiated tumor type." (PMID 33920544, 2021). "BRAF inhibitors together with MEK inhibitors could induce pyroptosis in melanoma with a higher HMGB1, more tumor-associated T cells, and less dendritic cell infiltration, while GSDME deficiency would reverse the anti-tumor immunity." (PMID 34298833, 2021). "Furthermore, HMGB1 knockdown was reported to enhance tumour cell viability and arrest apoptosis-related proteins through NF-κB in HepG2 cells." (PMID 34539874, 2021). "It has been found that Cabozantinib triggers the release of C-X-C motif chemokine ligand 12 (CXCL12) and high mobility group box 1 protein (HMGB1) from dying tumor cells, which mediate acute neutrophil mobilization and migration, contributing to an amplified anti-tumor response." (PMID 34830850, 2021). "DC maturation in the TME can be promoted by HMGB1 stimulated by preoperative chemoradiotherapy and is accompanied by surface molecule (CD80, CD86, CD208, and LAMP3) expression with anti-tumor functions of tumor-associated antigen presentation, which facilitates effective CD8+ T cell activation." (PMID 33995371, 2021). "Therapeutic resistance is one of the characteristics of tumor stemness, so we next explored whether the “RNA–RNA” crosstalk of HMGB1 and RICTOR can influence the therapeutic response of HCC." (PMID 34916485, 2021). "Cytoplasm-staining of HMGB1 in tumor cells was easily observed in most of the TMA cores." (PMID 34257571, 2021). "The influence of exogenous HMGB1 on the proliferation of residual tumor was observed." (PMID 34805222, 2021). "Targeting tumor cells by radiotherapy and chemotherapy causes the release of damage-associated molecular pattern (DAMP) molecules such as high mobility group box 1 (HMGB1) as a result of necrotic cell death, and it has been found that HMGB1 triggers immune responses." (PMID 34071939, 2021). "For example, tumor cells in the state of ferroptosis may shape cancer cell immunogenicity by releasing high mobility group box 1 (HMGB1) in an autophagy-dependent manner." (PMID 34726238, 2021). "High Mobility Group Box1 (HMGB1), a chromatin-binding nuclear protein, could facilitate autophagy after administration of cytotoxic agents in order to promote tumor cell survival." (PMID 33567616, 2021). "Furthermore, HMGB1 levels correlated with both the stage of disease and tumor size, and showed decreased levels after resection of the tumor." (PMID 33672622, 2021). "This was manifested by an increase in CD8+ TIL cells, Neutrophil (Ly6G + cells), tumor-specific T cells, Dendritic cells (CD11c+), high-mobility group box 1 (HMGB1), and activated CD8+ T cells (as indicated by intracellular interferon gamma (IFNγ) expression)) at 7–10 days post-treatment." (PMID 33827375, 2021). "This also opens up new possibilities that the secreted HMGB1 may also improve tumor cell survival and invasion." (PMID 34094941, 2021).
tumor (continued). "Previous studies demonstrated that both ICPs (e.g., PD-L1 and TIM-3) and immunogenic cell death (ICD) modulators (e.g., CALR and HMGB1) play critical roles in modulating the host anti-tumor immunity, which could influence the efficacy of mRNA vaccine." (PMID 33685460, 2021). "Our findings could contribute to cancer prevention via modulation of the HMGB1/TRIM30α/STING pathway to suppress tumor cell growth by inducing senescence." (PMID 33558529, 2021). "In addition, western blot analysis of CT26 tumor tissues showed that the extracellular and cytoplasmic HMGB1 was significantly enhanced in H@Gd-NCPs+RT (6 Gy × 1) group compared with Saline, RT (6 Gy × 1), Gd-NCPs + RT (6 Gy × 1) groups." (PMID 33420008, 2021). "HMGB1 is often overexpressed in the nuclei of cancer cells and embryonic cells, and this overexpression, along with dysfunction, is considered a marker of tumor and cancer progression." (PMID 33140586, 2021). "In this study, we identified that KDM4D/SYVN1 axis could modulate the post-transcriptional regulation of HMGB1, providing novel insights on HMGB1 accumulations in tumor." (PMID 34820329, 2021). "Mounting evidence has revealed the crucial role of HMGB1 in tumor progression." (PMID 33661757, 2021). "Interestingly, the site index of HMGB1 was moderately correlated with the tumor stage (r = 0.441, p = 0.031)." (PMID 35201494, 2021). "To test whether targeting HMGB1 is beneficial or detrimental in immunocompetent tumor‐bearing hosts, we set up a syngeneic model of MM, where mouse AB1 malignant mesothelioma cells are grafted into the peritoneum of syngeneic BALB/c mice." (PMID 33956406, 2021). "In addition, ATP and HMGB1 protein levels in both tumour cells and culture supernatant are significantly increased upon treatment with bullatacin." (PMID 34112202, 2021). "HMGB1, as a characteristic danger associated molecular pattern (DAMP) marker, was found to be elevated intracellularly and released into bodily fluids in various diseases, including poorly differentiated neoplasms." (PMID 33672622, 2021). "Additionally, we analyzed the expression of HMGB1 in the irradiation‐treated animal tumor bearing model." (PMID 33523579, 2021). "Immunostimulatory DAMPs include a release of endoplasmatic reticulum proteins like calreticulin and heat shock proteins (HSP), the toll-like receptor (TLR) 4 and TLR9 agonist high mobility group box 1 (HMGB1) and ATP, leading to DC recruitment and activation at the site of tumor cell death." (PMID 34025657, 2021). "In addition, HMGB1 was compared with established tumor markers cytokeratin 19-fragments (CYFRA 21-1), carcinoembryonic antigen (CEA) and neuron specific enolase (NSE)." (PMID 33672622, 2021). "We demonstrate that TLR2 blockade reduces the effects of tumour-secreted HMGB1 on macrophages." (PMID 33922955, 2021). "An important deduction herein is that Nano-DOX, by virtue of their RAGE-induction property, may also potentiate tumor cell RAGE interaction with HMGB1 derived from tumor stromal cells, e.g. the TAMs." (PMID 34488792, 2021). "HMGB1 is the third ligand for tumor-infiltrating DCs that expresses a high level of TIM-3." (PMID 34572263, 2021). "In the tumor tissue samples, HMGB1 expression levels have been analyzed at different locations (i.e., nuclear, cytoplasmic, extracellular), which may be associated with a different (functional) outcome." (PMID 33920544, 2021). "Similarly, treatment with IgG 2A11 resulted in lower levels of HMGB1 in the tumor extracts of the mice treated with IgG 2A11 than in the mice treated with the control IgGs (p < 0.001)." (PMID 33915939, 2021). "In vivo tumor xenograft models were used to determine whether the HMGB1 inhibition affected the malignant features of ESCC cells." (PMID 34820329, 2021). "We could infer that tumoral HMGB1 is one of the cachexic factors and exosomes containing HMGB1 might be one of the mediators between tumor and muscle." (PMID 34867338, 2021).
tumor (continued). "In NB, HMGB1 is highly expressed and considered as a tumor-promoting factor." (PMID 34889712, 2021). "Taken together, these results suggested that cytoplasmic HMGB1 could recruit macrophages into tumor tissue and participate in a heterogeneous TME that was associated with worse prognosis of UTUC." (PMID 34244567, 2021). "However, the T-cell immunoglobulin and mucin-domain containing-3 (TIM-3) highly expressed on tumor-infiltrating dendritic cells (TIDCs) interacts with the nuclear protein HMGB1 and suppresses nucleic acids sensing-mediated stimulation of DCs." (PMID 34078376, 2021). "Such tumor-promoting properties are common to HMGB1 (oxidative HMGB1); however, glycated HMGB1 is more pronounced, and it is thought that both types of HMGB1 might promote cancer in a cooperating manner." (PMID 34068442, 2021). "Typically, immunogenic cell death is associated with expression of surface calreticulin, release of HMGB1, release of ATP, whereas vaccination and tumor re-challenge assays have been considered as a standard in vivo approach to validating immunogenic cell death inducers." (PMID 34359580, 2021). "HMGB1 could elicit proinflammatory cascades and promote formation and metastasis of tumor, which is crucial for sustenance of tumor inflammatory microenvironment." (PMID 33925132, 2021). "Focusing on the intercellular events in the elimination of dying tumor cells, it was found that the absence of HMGB1 expression can attenuate DC-dependent T cell responses toward tumor-associated antigens." (PMID 32340275, 2020). "Moreover, some protein overexpression has a positive effect on HMGB1 overexpression and translocation to cytoplasm and extracellular matrix of tumor cells, making an inflammation context microenvironment." (PMID 33117687, 2020). "Indeed, HMGB1 has been used as a marker of necrosis in experimental studies of tumor pathophysiology." (PMID 32363191, 2020). "Extracellular HMGB1, known as a “danger signal”, also carries neoantigens from tumor cells, including fragments of DNA, to find specific pattern recognition receptors on DCs such as RAGE (receptor for advanced glycation end products) and TLR4 (Toll-like receptor-4, CD284)." (PMID 32872532, 2020). "Furthermore, in the control tumours we found only strong nuclear HMGB1 staining, whereas in the treated tumours HMGB1 was localised in the nuclei and cytoplasm." (PMID 33082328, 2020). "Notably, tumor cell-derived high-mobility group box 1 protein (HMGB1), which binds to toll-like receptor 4 (TLR4), has also been attributed to tumor cell-induced platelet aggregation." (PMID 32110917, 2020). "However, necrosis releases pro-inflammatory and tumor-promoting cytokine HMGB1 into the extracellular space reported to stimulate inflammation and angiogenesis, and promote tumor progression." (PMID 33027952, 2020). "HMGB1 and HMGB2 have been implicated in numerous cellular processes including proliferation, differentiation, DNA replication, recombination, repair, transcription, inflammation, tumor migration, and cell signaling." (PMID 33178199, 2020). "Post-expression of HMGB1 group and changes of liver function, tumor marker and immune after TACE." (PMID 33473353, 2020). "In a MPE, it is unknown whether HMGB1 has a role in anti-tumor immune activation or tumor progression." (PMID 33013860, 2020). "HMGB1 has also been reported to bind to T-cell immunoglobulin and mucin domain 3 (TIM-3) expressed by tumor-associated dendritic cells (DCs) in murine tumors and patients with cancer as one of several immunosuppressive mechanisms activated by this pleotropic protein." (PMID 32664328, 2020). "However, in neoplastic tissues, HMGB1 is actively secreted by inflammatory cells or tumor cells or passively released by dead cells, and it can activate its cognate receptors, including TLR2." (PMID 33321934, 2020).